COPB2 (coat protein complex I subunit beta 2)
Description:
The coatomer is a cytosolic protein complex that binds to dilysine motifs and reversibly associates with Golgi non-clathrin-coated vesicles, which further mediate biosynthetic protein transport from the ER, via the Golgi up to the trans Golgi network. Coatomer complex is required for budding from Golgi membranes, and is essential for the retrograde Golgi-to-ER transport of dilysine-tagged proteins. In mammals, the coatomer can only be recruited by membranes associated to ADP-ribosylation factors (ARFs), which are small GTP-binding proteins; the complex also influences the Golgi structural integrity, as well as the processing, activity, and endocytic recycling of LDL receptors. This coatomer complex protein, essential for Golgi budding and vesicular trafficking, is a selective binding protein (RACK) for protein kinase C, epsilon type. It binds to Golgi membranes in a GTP-dependent manner (By similarity).
Synonyms: Beta'-COP; betaprime-COP; MCPH19; OPDD
Tractability: Small molecule: a structure with a bound ligand is known. Antibody: UniProt places it where antibodies can reach, with medium confidence. PROTAC: ubiquitination databases record sites on it; its protein half-life has been measured.
Gene: Protein-coding gene on chromosome 3 (139,353,942 to 139,389,736, reverse strand). Ensembl gene ENSG00000184432.
Subcellular location: Cytoplasm, cytosol; Golgi apparatus membrane; Cytoplasmic vesicle, COPI-coated vesicle membrane
Subcellular location (Human Protein Atlas): Endoplasmic reticulum; Golgi apparatus
Pathways (Reactome):
Vesicle-mediated transport: COPI-dependent Golgi-to-ER retrograde traffic; COPI-mediated anterograde transport
Gene Ontology:
Molecular function: protein binding; structural molecule activity
Biological process: intra-Golgi vesicle-mediated transport; retrograde vesicle-mediated transport, Golgi to endoplasmic reticulum; endoplasmic reticulum to Golgi vesicle-mediated transport; intracellular protein transport; vesicle-mediated transport
Cellular component: COPI vesicle coat; cytosol; endoplasmic reticulum membrane; Golgi membrane; transport vesicle; COPI-coated vesicle membrane; Golgi apparatus; membrane coat
Genetic constraint (gnomAD): Loss-of-function variants: 12 observed, 109.6 expected, observed/expected ratio (o/e) 0.11, 90% interval 0.069 to 0.18. The upper end of that interval is the gene's LOEUF score, 0.18, which puts it in group 1 of 6, group 1 being the genes least tolerant of losing a copy. Missense variants: 754 observed, 1,063.8 expected, observed/expected ratio (o/e) 0.71, 90% interval 0.67 to 0.75. Synonymous variants: 314 observed, 362.07 expected, observed/expected ratio (o/e) 0.87, 90% interval 0.79 to 0.95.
Homologues: Orthologues: chimpanzee COPB2 (99% identical), macaque COPB2 (99% identical), dog COPB2 (99% identical), guinea pig COPB2 (99% identical), pig COPB2 (99% identical), rabbit COPB2 (98% identical), mouse Copb2 (98% identical), rat Copb2 (98% identical), tropical clawed frog copb2 (91% identical), zebrafish copb2 (90% identical), Drosophila melanogaster beta'COP (68% identical), Caenorhabditis elegans Y41C4A.32 (15% identical). Paralogues in human: COPA (26% identical).
Diseases named in the same sentence as COPB2 in open-access papers:
COPB2 is named in the same sentence as 59 diseases in open-access papers, as found by Europe PMC text mining. Sharing a sentence is not in itself a finding about the gene and the disease. The quoted sentences say what the papers report.
breast carcinoma (11 papers, 2012 to 2025). "For example, higher COPB2 expression is associated with lymph node metastasis of breast cancer, while COPB2 knockdown inhibits breast cancer cell proliferation and metastasis." (PMID 31926110, 2020). "Here, we found that COPB2 was significantly up‐regulated in a large cohort of human breast cancer tissues and that COPB2 levels significantly linked with the clinical characteristics of BC, including oestrogen receptor (ER) and BC lymph node metastasis." (PMID 31119859, 2019). "Current study reported that COPB2 was overexpressed which in turn was associated with human breast cancer promotion." (PMID 31119859, 2019). "Moreover, increased COPB2 expression is linked to higher pathological grading in colon cancer and lymph node metastasis in breast cancer." (PMID 35454945, 2022). "Moreover, COPB2 knockdown abolished SAG-induced breast cancer cell proliferation and invasion, which strongly suggests COPB2 signaling is involved in the mechanism underlying the oncogenic effect of SAG." (PMID 31926110, 2020). "COPB2 is responsible for the development of many human cancers, such as cutaneous squamous cell carcinoma, and breast cancer." (PMID 40191726, 2025). "Next, Coatomer subunit beta (COPB2) was downregulated in cervical cancer and upregulated in breast cancer." (PMID 36979661, 2023). "Increased expression and vital oncogenic roles of COPB2 in cancer progression have been elucidated in various types of cancers, such as breast cancer, gastric cancer, prostate cancer, and glioma." (PMID 35454945, 2022). "The results indicated that the phosphorylation sites of COPB2 exhibited an increasing trend in breast cancer, OV, and UCEC, whereas a decreasing trend was noted in colon cancer." (PMID 34676262, 2021). "At the protein level, the results from the CPTAC dataset indicated that the expression levels of total COPB2 protein were higher in tissues of breast cancer, ovarian cancer, colon cancer, clear cell RCC, UCEC, and LUAD than in nontumor tissues (P < 0.001)." (PMID 34676262, 2021). "Recently, COPB2 was reported to have important correlations with various cancer types and has different functions in different tumors, such as breast cancer, glioma, and prostate cancer." (PMID 33824874, 2021). "Subsequent in vitro experiments demonstrated that SAG and COPB2 act cooperatively to stimulate breast cancer cell proliferation, migration and invasion." (PMID 31926110, 2020). "Many studies have found that COPB2 was up-regulated in various human tumors, such as breast cancer, gastric cancer and glioma." (PMID 33211699, 2020). "To further evaluate the oncogenic effects of SAG and COPB2 in breast cancer cells, we performed a set of transwell migration and invasion assays." (PMID 31926110, 2020). "To further clarify the relationship between SAG and COPB2, we used the CBioPortal to examine the RNAseq data in a breast cancer cohort and showed that SAG is co-upregulated with COPB2." (PMID 31926110, 2020). "We then used RT-qPCR to measure the relative levels of SAG and COPB2 expression in three breast cancer cell lines (MCF-7, SKBR-3 and T47d) and in a normal breast cell line (MCF-10A)." (PMID 31926110, 2020). "Our findings show that SAG is associated with poorer survival in breast cancer, especially the luminal A subtype, and that there is highly correlated co-overexpression of SAG and COPB2 in breast cancers." (PMID 31926110, 2020). "The heat map generated using the UCSC Xena browser confirmed that SAG is highly co-upregulated with COPB2 in breast cancers." (PMID 31926110, 2020). "In order to further investigate the dysregulated expression of COPB2, RNA sequencing data of breast cancer were extracted from the TCGA database which contained with 1091 cases of BC patients and 228 pairs of patients with normal tissue." (PMID 31119859, 2019). "The expression of COPB2 mRNA expression was significantly up‐regulated in breast cancer tissues compared with the adjacent normal tissues (P < 0.001)." (PMID 31119859, 2019).
breast carcinoma (continued). "To demonstrate the function of COPB2 in breast cancer, we examined 56 matched BC tumour tissue and adjacent normal tissues." (PMID 31119859, 2019). "In order to validate the function of COPB2 in the breast cancer cell, we performed the cell migration and invasion assay." (PMID 31119859, 2019). "Through the whole transcriptome sequencing of 15 pairs of the breast tumour and adjacent normal tissues, we found that the expression level of COPB2 in breast cancer tissues was significantly higher than that in normal tissues." (PMID 31119859, 2019). "In order to assess the effects of COPB2 expression on the prognosis of breast cancer, we analysed follow‐up data of the TCGA cohort." (PMID 31119859, 2019). "Our study specifies new ideas and shreds evidence that COPB2 overexpression shows its significant roles in breast cancer progression." (PMID 31119859, 2019). "To validate the result of sequencing, we selected another 56 paired breast cancer tissues and adjacent non‐cancerous tissues to examine the expression of COPB2 mRNA by qRT‐PCR." (PMID 31119859, 2019). "With the sequencing technology, we found that coatomer protein complex subunit beta 2 (COPB2) gene is overexpressed in breast cancer tissues." (PMID 31119859, 2019). "Subsequently, we used the small interfering RNA (siRNA) to knockdown the expression of COPB2 in two types of breast cancer cell lines (MDA‐MB‐231 and BT‐549)." (PMID 31119859, 2019). "Clinical results in breast cancer patients and possible coefficient of correlation with COPB2, however, remain unidentified." (PMID 31119859, 2019). "This current research provides new shreds of evidence that COPB2 overexpression shows significant character in the progression of breast cancer." (PMID 31119859, 2019). "Though RT‐qPCR, the mRNA expression level of COPB2 was evaluated in a local cohort and different breast cancer cell lines." (PMID 31119859, 2019). "Our study aimed to determine the relationship between COPB2 expression and the role of COPB2 in the proliferation and metastasis in breast carcinoma." (PMID 31119859, 2019). "This signifies that COPB2 can predict the probability of LNM in breast cancer patients justifying additional investigations." (PMID 31119859, 2019). "In addition, data from the Human Protein Atlas (HPA) indicated that COPB2 was stably expressed in almost all patients with thyroid, lung, colon, head and neck, and breast cancers." (PMID 34676262, 2021). "As expected, knocking down SAG or COPB2 inhibited breast cancer cell proliferation." (PMID 31926110, 2020). "Notably, one recent qRT-PCR analysis revealed that COPB2 mRNA levels were significantly higher in breast cancer tissues than in normal tissues, suggesting COPB2 is a potential tumor oncogene in breast cancer." (PMID 31926110, 2020). "Taken together, our findings indicate that expression of SAG and COPB2 may be a useful prognostic indicator in breast cancer." (PMID 31926110, 2020). "We also detected highly correlated co-overexpression of SAG and COPB2 in breast cancers." (PMID 31926110, 2020). "Our findings suggest that levels of SAG and COPB2 expression may be useful prognostic indicators in breast cancers and that SAG may be involved in COPB2-related signaling during breast cancer development." (PMID 31926110, 2020). "Because both SAG and COPB2 exert pro-proliferative effects in several human cancers, we wanted to determinate how SAG and COPB2 knockdown influenced breast cancer cell proliferation, and whether SAG and COPB2 acted cooperatively to affect cell proliferation." (PMID 31926110, 2020). "We also observed that COPB2 is highly upregulated along with SAG in breast cancers." (PMID 31926110, 2020). "Furthermore, the expression of COPB2 in breast cancer tissues and adjacent non‐cancerous tissues was both analysed in a TCGA cohort and local cohort." (PMID 31119859, 2019).
breast carcinoma (continued). "In short, our research shows the increased expression of COPB2 in breast cancer in humans when compared to normal tissues and COPB2 may predict breast cancer metastasis and also it might be an independent molecular marker." (PMID 31119859, 2019). "High levels of COPB2 correlated with significantly lower survival rates in breast cancer patients." (PMID 22745748, 2012). "Moreover, this relationship between SAG and COPB2 was most significant in luminal B breast cancers." (PMID 31926110, 2020). "Moreover, SAG may be involved in a COPB2-related signaling pathway that plays an oncogenic role in breast cancer." (PMID 31926110, 2020). "In the present study, we found that COPB2 is upregulated along with SAG in breast cancers and that both are highly expressed in breast cancer cell lines." (PMID 31926110, 2020). "In this study, by integrating CRISPR-CAS9 functional genomics (DEPMAP database) and TCGA multi-omics data, seven key genes (CDK7, CLTC, COPB2, CRNKL1, GSPT1, NSF and PSMD12) that are closely related to the proliferation and prognosis of breast cancer were systematically identified." (PMID 40657358, 2025). "We found that gene expression of both SAG and COPB2 was higher in all three breast cancer cell lines than in normal breast tissue cells." (PMID 31926110, 2020). "We found that SAG or COPB2 knockdown significantly inhibited breast cancer cell migration and invasion as compared to the control group, while ectopic overexpression of SAG slightly enhanced breast cancer cell migration and invasion." (PMID 31926110, 2020). "Here, we confirmed upregulation of COPB2 in three breast cancer cell lines, but not in normal breast epithelial cells." (PMID 31926110, 2020). "This current research demonstrates, significant up‐regulation of COPB2 in tissues of breast cancer while comparing the adjacent normal tissue both invalidated cohort and TCGA cohort." (PMID 31119859, 2019). "We quantitatively analyzed the expression profiles of 160 proteins in MDA-MB-231 breast cancer cells 48 or 72 hours post-infection with non-targeting control siRNA or siRNA targeting COPB2 or COPG2." (PMID 22745748, 2012).
gastric cancer (10 papers, 2020 to 2026). A primary or metastatic malignant neoplasm involving the stomach. "In gastric cancer, COPB2 can affect the growth and apoptosis of gastric cancer cell lines via the RTK signaling pathway." (PMID 33824874, 2021). "Moreover, it has been proven that reduced expression of COPB2 induces cellular apoptosis and inhibits cell growth and invasion in gastric cancer, similar to previously studied tumors." (PMID 38355574, 2024). "In gastric cancer, COPB2 is regulated by let-7a, which acts as a molecular sponge for H19." (PMID 38355574, 2024). "In lung cancer cells, COPB2 inhibits apoptosis and promotes cell proliferation and tumorigenesis through up-regulation of YAP1 expression, while COPB2 knockdown in gastric cancer cells suppresses cell proliferation and promotes apoptosis by repressing the RTK signaling cascade." (PMID 31926110, 2020). "This study investigated the role of COPB2 in gastric cancer (GC) pathogenesis." (PMID 41618837, 2026). "COPB2 silencing also promotes the activation of the RTK and JNK/c-Jun signaling pathways in gastric cancer and CRC." (PMID 34101128, 2021). "The knockdown of COPB2 in gastric cancer cell lines suppressed colony formation and promoted apoptosis via the inhibition of RTK signaling and downstream signaling cascade molecules, which suggests that COPB2 is a potential target for gene silencing for the treatment of gastric cancer." (PMID 34101128, 2021).
lung adenocarcinoma (10 papers, 2019 to 2023). A carcinoma that arises from the lung and is characterized by the presence of malignant glandular epithelial cells. "Puet al. found that in NCI-H1975 lung adenocarcinoma cell line, miRNA-335-3p downregulates the expression of coatomer protein complex subunit β2 (COPB2) to inhibit cell proliferation, migration and invasion and promote cell apoptosis." (PMID 37723874, 2023). "In lung adenocarcinoma, patients with increased COPB2 expression showed advanced clinical symptoms more often, such as low pathological grade, presence of lymph node metastasis, higher TNM stage, presence of distant metastasis, and worse overall survival." (PMID 35454945, 2022). "In the lung adenocarcinoma cells, miR-335-3p was targeted and down-regulated by the Coatomer Protein Complex Subunit beta 2 (COPB2) Gene." (PMID 35739866, 2022). "In lung adenocarcinoma cells, COPB2 overexpression attenuated apoptosis and promoted both proliferation and tumorigenesis via upregulation and nuclear translocation of YAP1 in vitro." (PMID 35454945, 2022). "Similar to the observations on miR-4461 in CRC, miR-335-3p and miR-216a-3p have been found to target the 3′UTR of COPB2, which led to the inhibition of COPB2 in lung adenocarcinoma (LUAD) and lung cancer cell lines, respectively." (PMID 34101128, 2021). "Pu et al7 reported that COPB2 upregulation in lung adenocarcinoma cell lines facilitates cell growth and tumorigenesis via upregulating YAP1 expression." (PMID 31710183, 2020). "We manipulated a lung adenocarcinoma cell line PC9‐derived EVs which are positive for COPB2." (PMID 34122778, 2021). "In lung adenocarcinoma, COPB2 was confirmed to be overexpressed and negatively correlated with survival, and COPB2 downregulation enhanced apoptosis and repressed proliferation and tumorigenesis in lung adenocarcinoma cells." (PMID 33824874, 2021). "COPB2 was reported to promote cell proliferation and tumorigenesis through up-regulating YAP1 expression in lung adenocarcinoma cells." (PMID 35715770, 2022).
prostate carcinoma (8 papers, 2019 to 2022). A carcinoma that arises from epithelial cells of the prostate gland. "In prostate cancer, COPB2 has also been shown to be highly expressed and can promote PC-3 cell proliferation and inhibit apoptosis by affecting its cell cycle." (PMID 33824874, 2021). "This study explored the role and the downstream mediators of COPB2 in prostate cancer (PCa)." (PMID 35600351, 2022). "Moreover, reduced expression of COPB2 induced cellular apoptosis and inhibited cell growth in prostate cancer." (PMID 34150620, 2021). "COPB2 levels reportedly correlated with the occurrence and development of tumors, such as PC3 prostate cancer." (PMID 33211699, 2020).